LRP4 (LDL receptor related protein 4)
Description:
Mediates SOST-dependent inhibition of bone formation. Functions as a specific facilitator of SOST-mediated inhibition of Wnt signaling. Plays a key role in the formation and the maintenance of the neuromuscular junction (NMJ), the synapse between motor neuron and skeletal muscle. Directly binds AGRIN and recruits it to the MUSK signaling complex. Mediates the AGRIN-induced phosphorylation of MUSK, the kinase of the complex. The activation of MUSK in myotubes induces the formation of NMJ by regulating different processes including the transcription of specific genes and the clustering of AChR in the postsynaptic membrane. Alternatively, may be involved in the negative regulation of the canonical Wnt signaling pathway, being able to antagonize the LRP6-mediated activation of this pathway. More generally, has been proposed to function as a cell surface endocytic receptor binding and internalizing extracellular ligands for degradation by lysosomes. May play an essential role in the process of digit differentiation (By similarity). (Microbial infection) Functions as a receptor for yellow fever virus.
Synonyms: LRP-4; LRP10; MEGF7; CLSS; SOST2; CMS17
Tractability: Antibody: UniProt places it where antibodies can reach, with medium confidence; UniProt predicts a signal peptide or a membrane-spanning region; its Gene Ontology location is reachable by antibodies, with medium confidence. PROTAC: ubiquitination databases record sites on it; its protein half-life has been measured.
Gene: Protein-coding gene on chromosome 11 (46,856,717 to 46,918,642, reverse strand). Ensembl gene ENSG00000134569.
Subcellular location: Cell membrane
Subcellular location (Human Protein Atlas): Mitochondria; Nucleoplasm
Pathways (Reactome):
Extracellular matrix organization: ECM proteoglycans
Gene Ontology:
Molecular function: protein binding; virus receptor activity; receptor tyrosine kinase binding; scaffold protein binding; apolipoprotein binding; calcium ion binding; coreceptor activity; protein homodimerization activity
Biological process: amyloid-beta clearance by cellular catabolic process; kidney development; limb development; negative regulation of canonical Wnt signaling pathway; negative regulation of ossification; dendrite morphogenesis; generation of neurons; negative regulation of axonogenesis; positive regulation of presynaptic membrane organization; postsynaptic membrane assembly; presynaptic membrane assembly; skeletal muscle acetylcholine-gated channel clustering; synapse organization; synaptic assembly at neuromuscular junction; enzyme-linked receptor protein signaling pathway; positive regulation of Rac protein signal transduction; positive regulation of skeletal muscle acetylcholine-gated channel clustering; regulation of postsynapse assembly; symbiont entry into host cell; system development
Cellular component: cell surface; dendrite; neuromuscular junction; neuronal cell body; plasma membrane; plasma membrane raft; postsynaptic density; synaptic membrane; synapse
Genetic constraint (gnomAD): Loss-of-function variants: 92 observed, 218.49 expected, observed/expected ratio (o/e) 0.42, 90% interval 0.35 to 0.5. The upper end of that interval is the gene's LOEUF score, 0.5, which puts it in group 2 of 6, group 1 being the genes least tolerant of losing a copy. Missense variants: 1,897 observed, 2,630.5 expected, observed/expected ratio (o/e) 0.72, 90% interval 0.69 to 0.75. Synonymous variants: 893 observed, 985.46 expected, observed/expected ratio (o/e) 0.91, 90% interval 0.86 to 0.96.
Gene-disease validity (ClinGen):
ClinGen rates the evidence that LRP4 causes each of these diseases.
Cenani-Lenz syndactyly syndrome (autosomal recessive): Definitive. Cenani-Lenz syndrome (CLS) is a congenital malformation syndrome that associates a complex syndactyly of the hands with malformations of the forearm bones and similar manifestations in the lower limbs.
congenital myasthenic syndrome 17 (autosomal recessive): Limited.
Homologues: Orthologues: macaque LRP4 (99% identical), dog LRP4 (98% identical), chimpanzee LRP4 (97% identical), guinea pig LRP4 (97% identical), rabbit LRP4 (97% identical), pig LRP4 (97% identical), mouse Lrp4 (97% identical), rat Lrp4 (97% identical), tropical clawed frog lrp4 (77% identical), zebrafish lrp4 (38% identical), Drosophila melanogaster arr (27% identical). Paralogues in human: LRP6 (32% identical), LRP5 (31% identical), LRP1 (28% identical), LRP1B (26% identical), LRP2 (25% identical), VLDLR (14% identical), LRP8 (13% identical), EGF (9% identical), NID1 (9% identical), NID2 (8% identical), LRP12 (6% identical), and 2 more.
Diseases named in the same sentence as LRP4 in open-access papers:
LRP4 is named in the same sentence as 90 diseases in open-access papers, as found by Europe PMC text mining. Sharing a sentence is not in itself a finding about the gene and the disease. The quoted sentences say what the papers report.
myasthenia gravis (70 papers, 2014 to 2026). Myasthenia gravis (MG) is a rare, clinically heterogeneous, autoimmune disorder of the neuromuscular junction characterized by fatigable weakness of voluntary muscles. "Mutations in LRP4 or MuSK and autoantibodies directed against these proteins cause congenital myasthenic syndromes and myasthenia gravis, respectively." (PMID 37356721, 2023). "Remarkably, functional alterations of Lrp4 using blocking antibodies or specific mutations, both observed in human patients, induce Myasthenia gravis and a form of Congenital myasthenic syndrome, respectively." (PMID 34944540, 2021). "In humans, 5–10% cases of myasthenia gravis are caused by autoantibodies against MuSK, which prevent binding between MuSK and Lrp4, and inhibit agrin-stimulated MuSK phosphorylation." (PMID 25540609, 2014). "It would also be of interest to evaluate whether ColQ or LRP4 identified mutations or autoantibodies, responsible for congenital myasthenia or myasthenia gravis, disrupt or diminish the interaction between LRP4 and ColQ." (PMID 37356721, 2023). "Acetylcholine receptor antibodies (AChR), muscle-specific kinase (MuSK), and lipoprotein-associated protein (LRP4) have been well established as sensitive diagnostic markers and pathogens, in addition to antibodies in the classification of patients with Myasthenia gravis also play a key role." (PMID 34930325, 2021). "Further underscoring its importance in nervous system function and highlighting a potential link to human disease, the loss of LRP4 is linked to multiple neurodegenerative diseases including myasthenia gravis, amyotrophic lateral sclerosis (ALS), and Alzheimer’s disease." (PMID 33799485, 2021). "Auto-antibodies against MuSK and LRP4 cause Myasthenia gravis, whereas mutations affecting the function of each of these proteins are involved in Myasthenic Congenital Syndromes, thus demonstrating the requirement of these postsynaptic proteins for mature NMJ maintenance." (PMID 32848618, 2020). "Moreover, autoantibodies to Agrin, Lrp4, or MuSK cause myasthenia gravis (MG), which is likewise distinct from ALS." (PMID 29460776, 2018). "These include acetylcholine receptor (AChR), muscle-specific kinase (MuSK), lipoprotein receptor-related protein 4 (Lrp4), all associated with myasthenia gravis (MG), and voltage-gated calcium channel (VGCC) associated with PNS Lambert-Eaton myasthenic syndrome (LEMS)." (PMID 27577085, 2016). "Lrp4 plays a key role in the formation and maintenance of neuromuscular synapses, as a loss of Lrp4 leads to a failure to form neuromuscular synapses, and mutations in Lrp4 or auto-antibodies to Lrp4 cause congenital myasthenia and myasthenia gravis, respectively." (PMID 25407677, 2014). "Myasthenia gravis (MG) is a rare autoimmune disease characterized by the production of autoantibodies that target the nicotinic acetylcholine receptors (AChRs) or functionally related proteins (MuSK and LRP4), which disrupt neuromuscular transmission causing pronounced skeletal muscle weakness." (PMID 39657004, 2025). "Background and Aims: Autoantibodies to the lipoprotein receptor‐related protein‐4 (anti‐LRP4) have been reported in a minority of patients with Myasthenia Gravis (MG), with potential pathogenic role and uncertain clinical relevance." (PMID 40542608, 2025). "Myasthenia gravis (MG) is a rare autoimmune disorder caused by specific antibodies against antigenic determinants of the neuromuscular junction, the main being nicotinic acetylcholine receptor (AChR), less frequently muscle‐specific tyrosine kinase (MuSK) or lipoprotein‐related protein 4 (LRP4)." (PMID 38164996, 2024). "Consistent with this hypothesis and given its well-known roles in the peripheral nervous system and NMJ function, recent work implicated LRP4 in disorders of the motor unit, specifically myasthenia gravis (MG), congenital myasthenic syndrome (CMS), and amyotrophic lateral sclerosis (ALS)." (PMID 33799485, 2021).
myasthenia gravis (continued). "Patient-derived AChR, MuSK, and LRP4 autoantibodies in MG are demonstrably pathogenic (B cells in the pathophysiology of myasthenia gravis), and patients most often harbor only one of these autoantibody specificities." (PMID 33061827, 2020). "Recent studies suggested that antibody to low-density lipoprotein receptor-related protein 4 (LRP4) was a pathogenic agent of myasthenia gravis (MG), and it was also detected in ALS patients." (PMID 27863479, 2016). "Due to the paucity of relevant case reports, The specific manifestations of myasthenia gravis with double-sero-positive AChR/LRP4 antibodies combined with muscle atrophy cannot be clarified." (PMID 40356916, 2025). "Positive antibodies (Anti-AChR, Anti-MuSK, LRP4) and electromyography aid in diagnosis, and approximately 10% of myasthenia gravis patients can also have thymoma." (PMID 39624461, 2024). "There are also other forms of myasthenia gravis with antibodies directed to other structures, such as anti-MuSK (muscle-specific kinase) antibodies, anti-Lrp4 (low-density lipoprotein receptor-related protein 4) antibodies, or anti-agrin antibodies." (PMID 37891867, 2023). "This study aimed to summarize the clinical characteristics and prognosis of patients with anti- acetylcholine receptor (AChR) positive myasthenia gravis (MG) with a combination of anti-LRP4 or Titin antibodies." (PMID 35614931, 2022). "Additional findings indicate that LRP4 plays a role in disorders of the nervous system, including myasthenia gravis, amyotrophic lateral sclerosis, and Alzheimer’s disease, demonstrating the need for further study to understand disease etiology." (PMID 33799485, 2021). "Myasthenia gravis (MG) is an acquired autoimmune disorder caused by autoantibodies binding acetylcholine receptors (AChR), muscle‐specific kinase (MuSK), agrin or low‐density lipoprotein receptor‐related protein 4 (Lrp4)." (PMID 34228850, 2021). "Other autoantibodies related to myasthenia gravis, such as low-density lipoprotein receptor-related protein 4 (LRP4) and anti-striational antibodies were positive in seven patients (4.9%)." (PMID 35111450, 2021). "LRP4 autoantibodies are detected in some patients with myasthenia gravis (MG), and the inhibition of the LRP4-agrin interaction appears to be responsible, at least in part, for their pathogenicity." (PMID 34849350, 2021). "The active immunization of mice with Lrp4 was proved to induce myasthenia gravis; the pathogenicity of Lrp4 antibodies was confirmed by the study in animal models that showed both pre- and post-synaptic impairments and active complements." (PMID 32547365, 2020). "LRP4 plays a key role at the neuromuscular junction, and autoantibodies against LRP4 have been detected in some cases of myasthenia gravis." (PMID 31698687, 2019). "LRP4 has also been implicated in disorders, such as amyotrophic lateral sclerosis (ALS) and myasthenia gravis, in which impaired communication between nerves and muscles causes muscles to weaken." (PMID 28606304, 2017). "Recent work implicated LRP4 in both amyotrophic lateral sclerosis (ALS) and myasthenia gravis (MG), two debilitating motor disorders with a worldwide prevalence of ~1/5000." (PMID 28606304, 2017). "Our data confirm LRP4 as a new autoimmune target, supporting the value of including anti-LRP4 antibodies in further studies on Myasthenia gravis." (PMID 26284792, 2015). "These subgroups include AChR antibody‐positive generalized, ocular or thymoma‐associated myasthenia gravis, MuSK (muscle‐specific tyrosine kinase) and LRP4 (low density lipoprotein receptor‐related protein 4) antibody‐positive myasthenia gravis, and seronegative myasthenia gravis." (PMID 40298067, 2025). "Myasthenia gravis (MG) is a rare disease of the neuromuscular junction caused by Abs against postsynaptic membrane proteins, such as the acetylcholine receptor (AChR), the muscle-specific tyrosine kinase (MuSK), or the low-density receptor-related protein 4 (LRP4)." (PMID 32431692, 2020).
myasthenia gravis (continued). "Myasthenia gravis (MG) is a rare autoimmune disease caused by autoantibodies against neuromuscular junction proteins; the nicotinic acetylcholine receptor (AChR), the muscle specific tyrosine kinase (MuSK) or the low-density lipoprotein receptor-related protein 4 (LRP4)." (PMID 25915571, 2015). "It is currently unclear whether patients with Cenani–Lenz syndrome, Lrp4 congenital myasthenia, or auto-immune Lrp4 myasthenia gravis have cognitive deficits or neurological complications." (PMID 25407677, 2014). "Currently, the NIMBLE trial (Phase III randomized, placebo-controlled trial) is evaluating pozelimab + cemdisiran in both AChR and LRP4 myasthenia gravis patients, with the primary outcome being the MG-ADL score at 24 weeks." (PMID 40422242, 2025). "Studies indicated LRP4 antibodies are less frequent in the Chinese population compared to Westerners, as they were only found in 1–2.9% of SNMG and 0.8–1.7% of all MG cases, and mostly associated with ocular myasthenia gravis (OMG)." (PMID 39968461, 2025). "Autoimmune myasthenia gravis (MG) also compromises the NMJ signal transduction but is caused by autoantibodies against the acetylcholine receptor (AChR), muscle-specific receptor tyrosine kinase (MuSK), low-density lipoprotein receptor-related protein 4 (LRP4), or others." (PMID 36835142, 2023). "Myasthenia gravis (MG) is an autoimmune disease caused by pathogenic autoantibodies targeting the neuromuscular junction (NMJ); these include anti-acetylcholinereceptor (AchR), anti–muscle-specific tyrosine kinase (MuSK), and anti–low-density lipoprotein receptorrelated protein 4 (LRP4) antibodies." (PMID 35873770, 2022). "Observations indicate that patients with different subtypes of myasthenia gravis, associated with the presence of different antibodies—AChR, MuSK, or against lipoprotein receptor-related protein 4 (LRP4)—present similar clinical symptoms, regardless of the mechanism of immunopathology." (PMID 34439676, 2021). "Myasthenia gravis (MG) is an organ-specific rare autoimmune disorder of neuromuscular junction where auto-antibodies are directed to the nicotinic acetylcholine receptor (nACHR), the muscle-specific tyrosine kinase (MuSK) or lipoprotein receptor-related protein 4 (LRP4)." (PMID 32642338, 2020). "Moreover, auto-antibodies to Lrp4 are responsible for one form of myasthenia gravis." (PMID 25407677, 2014). "Antibody-negative myasthenia gravis refers to cases of MG in which AChR, MuSK, or LRP4 antibodies are undetectable." (PMID 40689326, 2025). "Myasthenia Gravis (MG) is a chronic autoimmune disease mediated by antibodies against the acetylcholine receptor (AChR), Muscle-Specific Kinase (MuSK) or other proteins in the neuromuscular junction such as Low-Density Lipoprotein Receptor Related Protein-4 (LRP4)." (PMID 37849836, 2023). "Myasthenia gravis (MG) is an autoimmune disease in which antibodies bind to acetylcholine receptors (AChR) or to other functional molecules, such as muscle-specific kinase (MuSK) and lipoprotein-receptor-related protein 4 (LRP4), in the postsynaptic membrane at the neuromuscular junction (NMJ)." (PMID 33633666, 2021). "Based on the mechanism of autoimmune disease and antibodies, invasive skeletal muscle molecules, thymus status, genetic characteristics, disease phenotype and response to treatment, myasthenia gravis is divided into early and late ocular subtypes (OMG), seronegative, thymoma, LRP4, MuSk." (PMID 34930325, 2021). "Fifth, this study measured only the concentrations of AchR-Ab in all patients with MG but did not measure other myasthenia gravis-related antibodies, such as anti-MuSK antibodies, anti-LRP4 antibodies, anti-titin, and anti-RyR antibodies, in all the patients." (PMID 35265719, 2022). "Acetylcholine receptor (AChR), MuSK, and LRP4 antibodies were all negative, consistent with seronegative ICI-induced myasthenia gravis." (PMID 42261457, 2026).
amyotrophic lateral sclerosis (16 papers, 2015 to 2024). Amyotrophic lateral sclerosis (ALS) is a neurodegenerative disease characterized by progressive muscular paralysis reflecting degeneration of motor neurons in the primary motor cortex, corticospinal tracts, brainstem and spinal cord. "Lrp4 and Agrin antibodies have also been detected in patients with amyotrophic lateral sclerosis (ALS), and their pathogenic role in MG and ALS is unclear." (PMID 31269763, 2019). "In some unclear situations, anti-LRP4-ab - cannot therefore distinguish reliably MG from amyotrophic lateral sclerosis." (PMID 39555481, 2024). "Co-occurrence of autoimmune diseases in LRP4-MG patients has rarely been reported, whereas LRP4 Abs were detected in 23.4% of patients with amyotrophic lateral sclerosis." (PMID 37781409, 2023). "The significance of LRP4 in nervous system function is further highlighted by its association with several human neurodegenerative diseases, including myasthenia gravis, amyotrophic lateral sclerosis (ALS) and Alzheimer’s disease." (PMID 37091972, 2023). "For example, LRP4 autoantibodies have been detected in some patients with amyotrophic lateral sclerosis (ALS) who presented with myasthenic symptoms." (PMID 32547535, 2020). "Furthermore, LRP4-Ab are present in up to 23% of amyotrophic lateral sclerosis (ALS) patients, a percentage of patients with other neuroimmune disorders, and up to 20% of subjects with MuSK-MG (as defined by serological and clinical criteria)." (PMID 33923771, 2021). "An auto-immune mechanism with LRP4 may also function in the motor disorder amyotrophic lateral sclerosis (ALS), as some ALS patient populations also have LRP4 autoantibodies." (PMID 33799485, 2021). "In the nervous system, Lrp4 participates in CNS development, cognitive function and plasticity, adult hippocampal neurogenesis, amyotrophic lateral sclerosis (ALS), and Aβ clearance in Alzheimer’s disease." (PMID 34063992, 2021). "Interestingly, LRP4 antibodies have also been reported in 10–23% of amyotrophic lateral sclerosis (ALS) patients and in 3.6% patients with other neurological diseases but not in healthy controls." (PMID 33329350, 2020). "Interestingly, LRP4 antibodies have also been detected in 10–23% of amyotrophic lateral sclerosis (ALS) patients and are thus not exclusively specific for MG." (PMID 32117321, 2020).